TMEM222 (transmembrane protein 222)
Synonyms: C1orf160; DKFZP564D0478; NEDMOSBA
Tractability: Antibody: UniProt predicts a signal peptide or a membrane-spanning region; the Human Protein Atlas places it where antibodies can reach. PROTAC: ubiquitination databases record sites on it.
Gene: Protein-coding gene on chromosome 1 (27,322,139 to 27,336,401, forward strand). Ensembl gene ENSG00000186501.
Subcellular location: Membrane; Cell projection, dendrite
Subcellular location (Human Protein Atlas): Cytosol; Plasma membrane; Cell Junctions
Gene Ontology:
Molecular function: protein binding
Cellular component: dendrite; membrane
Genetic constraint (gnomAD): Loss-of-function variants: 18 observed, 23.86 expected, observed/expected ratio (o/e) 0.75, 90% interval 0.52 to 1.12. The upper end of that interval is the gene's LOEUF score, 1.12, which puts it in group 4 of 6, group 1 being the genes least tolerant of losing a copy. Missense variants: 296 observed, 277.25 expected, observed/expected ratio (o/e) 1.07, 90% interval 0.97 to 1.17. Synonymous variants: 131 observed, 109.28 expected, observed/expected ratio (o/e) 1.2, 90% interval 1.04 to 1.39.
Homologues: Orthologues: macaque TMEM222 (99% identical), dog TMEM222 (95% identical), rat Tmem222 (95% identical), guinea pig TMEM222 (95% identical), mouse Tmem222 (94% identical), chimpanzee TMEM222 (90% identical), pig TMEM222 (89% identical), rabbit TMEM222 (75% identical), tropical clawed frog tmem222 (62% identical), zebrafish tmem222b (61% identical), zebrafish tmem222a (60% identical), Drosophila melanogaster CG8372 (49% identical), and 1 more.
Diseases named in the same sentence as TMEM222 in open-access papers:
TMEM222 is named in the same sentence as 1 disease in open-access papers, as found by Europe PMC text mining. Sharing a sentence is not in itself a finding about the gene and the disease. The quoted sentences say what the papers report.
neurodevelopmental disorder (1 paper, 2023). A behavioral and cognitive disorder with onset during the developmental period that involves impaired or aberrant development of intellectual, motor, or social functions. "DUF7788, a family of uncharacterized transmembrane proteins, includes not only A. thaliana RTE1 (ethylene signaling) but also human TMEM222 (C1orf160) predominantly found in brain, and deleterious variants of which correlate with neurodevelopmental disorders." (PMID 37164157, 2023).